INS (insulin)
Diseases named in the same sentence as INS in open-access papers (continued):
Sharing a sentence is not in itself a finding about the gene and the disease.
diabetes (continued). "A recent umbrella meta-analysis found that vitamin D supplementation significantly reduced fasting blood sugar, HbA1c, insulin concentrations, and homeostatic model assessment for insulin resistance and suggested that vitamin D supplementation may be beneficial for diabetes mellitus (DM) management." (PMID 39015860, 2024). "Type 2 diabetes mellitus (T2DM) is characterized by insulin resistance and insufficient insulin secretion and accounts for more than 90% of all types of DM worldwide." (PMID 38472622, 2024). "Moreover, it implies that the Paleolithic diet may enhance insulin homeostasis and glucose metabolism, rendering it a favorable dietary paradigm for individuals with diabetes." (PMID 38800782, 2024). "Additionally, AM TCRs did not mimic diabetes-associated proteins such as insulin, the insulin receptor, glucagon, or the glucagon receptor." (PMID 38339075, 2024). "DKA, typical but not exclusive of patients with type 1 diabetes mellitus (T1DM) or insulin-deficient diabetes, is characterized by hyperglycemia, metabolic acidosis with elevated anion gap due to increased ketone body concentrations, and variable degrees of osmolality and dehydration." (PMID 38594758, 2024). "Diabetes mellitus (DM) is a heterogeneous group of diseases with multiple aetiologies characterized by hyperglycaemia resulting from inadequate insulin secretion, inadequate insulin action or both." (PMID 38686463, 2024). "However, for stable patients, oral or non-insulin injectable agents (either alone or in combination) may be preferred, unless optimal diabetes control cannot be attained." (PMID 38559691, 2024). "Diabetes mellitus (DM) is a chronic syndrome of multiple etiology resulting from the lack and/or inability of insulin to exert its effects adequately." (PMID 38398867, 2024). "Routine screening for lipohypertrophy and intensive patient education on the proper insulin injection technique, including site rotation and needle single-use, may have a beneficial effect on better diabetes control, insulin dosing, and prevention of long-term complications of the disease." (PMID 38215209, 2024). "This outcome holds significant potential for enhancing patient compliance and reducing hospitalization costs for individuals with type 1 and type 2 diabetes mellitus (DM), who typically require daily insulin injections to maintain stable blood glucose levels." (PMID 39065572, 2024). "Diabetes mellitus (DM) is a widespread and impactful metabolic disorder marked by chronic hyperglycemia due to defects in insulin secretion or action." (PMID 39458946, 2024). "People with diabetes, particularly those with reduced insulin production, may benefit from this." (PMID 38465169, 2024). "Furthermore, porcine insulin has been used as an established and effective diabetes therapy for over 2 decades, demonstrating that pig islets may serve as a promising alternative cell source for ITx." (PMID 39553396, 2024). "Furthermore, curcumin can suppress ERK/JNK phosphorylation in insulin resistance cells generated by high glucose (HG) and promote the PI3K-AKT-GSK3B signaling pathway, hence increasing insulin sensitivity, providing a novel avenue for targeted diabetes treatment." (PMID 39834811, 2024). "The dysfunction in the INS gene may contribute to the onset of diabetes mellitus." (PMID 38673052, 2024). "The proband’s maternal grandfather was also diagnosed with diabetes and hypertension at the age of 30 years and was on treatment with oral antihypertensive and oral hypoglycemic agents for about 1 year before switching to insulin in view of uncontrolled diabetes." (PMID 39420905, 2024). "However, with urbanization (abundance of carbohydrate rich food, lack of physical activity and chronic stress) increased insulin demand leads to insulin deficiency, which along with IR precipitates into diabetes, even in LTBI subjects." (PMID 38327565, 2024).
diabetes (continued). "Diabetes mellitus (DM) is a chronic metabolic disease characterized by a high blood sugar level due to impairment in either insulin secretion, insulin action, or both." (PMID 39459569, 2024). "This comprehensive review delves into the potential of intranasal insulin delivery for managing Alzheimer's Disease (AD) while exploring the connection between AD and diabetes mellitus (DM)." (PMID 38441832, 2024). "Recent results show that vitamin D delays the onset of diabetes and complications, intervening through different mechanisms as follows: it decreases oxidative stress, inhibits apoptosis, increases calcium influx, stimulates insulin secretion, and decreases insulin resistance." (PMID 39457127, 2024). "Therefore, diabetes may increase the abundance of harmful bacteria in the intestinal flora to aggravate intestinal inflammation and insulin resistance." (PMID 39125375, 2024). "LVMI was positively associated with diabetes duration, age, hypertension history, SBP, using of DDP‐4i, CCBs, WC, WHR, VFA, SFA, VFA/H2, VFA/weight, BUN, Cr, and baPWV, but negatively associated with using of thiazolidinediones, insulin, and e‐GFR in both males and females." (PMID 39511977, 2024). "These providers are typically physicians and diabetes educators (primarily pharmacists, dietitians, and nurses with additional training), who feel unprepared to offer physical activity interventions safely and effectively to patients using insulin or with more complex disease presentations." (PMID 39407129, 2024). "While it was hypothesized that those in the insulin-taking group may be prioritizing dietary quality to manage diabetes and, thus, exhibit higher HEI-2015 scores, the insulin-taking group had an even lower dietary quality than the healthy group in this pilot study." (PMID 39458437, 2024). "Thus far, clinical studies have been widely performed on microfluidic-based diabetes monitoring, especially glucose sensing, yet technologies for the delivery of insulin and other drugs to diabetic patients with microfluidics are still mostly in the preclinical stage." (PMID 38509342, 2024). "In conclusion, diabetes caused by the pathogenic variant R46Q in the insulin gene may be effectively treated with noninsulin." (PMID 39027635, 2024). "Diabetes mellitus (DM) is a metabolic disorder that is characterized by chronic hyperglycemia due to an absolute or relatively insufficient amount of secreted insulin." (PMID 38741742, 2024). "Diabetes mellitus (DM) is a chronic metabolic disorder that results from insufficient insulin production or the body’s inability to utilize insulin." (PMID 39323638, 2024). "Finally, investigating the potential of integrating digital mental health interventions with other digital health tools, such as continuous glucose monitors or insulin pumps, could lead to more comprehensive and effective diabetes management systems." (PMID 39595455, 2024). "Furthermore, YG8R mice exhibited very mild, without significance, changes in insulin sensitivity compared with Y47 mice at 16 weeks of age, suggesting a late diabetes manifestation under FXN-deficient conditions." (PMID 39191875, 2024). "Others showed that increasing FFAs failed to potentiate insulin secretion in response to mixed meals and to intravenous glucose in non-diabetic subjects without a family history of diabetes, suggesting that genetic predisposition also plays an essential role in lipid regulation of GSIS." (PMID 38642584, 2024). "Although insulin treatment can have a major effect in controlling patients’ glycaemic levels, it may only have a subtle effect on the QoL of patients and family members because most of them have been living with diabetes for a long time." (PMID 38530614, 2024). "Diabetes mellitus (DM) is a group of chronic metabolic diseases characterized by abnormal glucose metabolism due to defective insulin production and/or insulin action." (PMID 39595537, 2024).
diabetes (continued). "From insulin’s initial extraction in the early 20th century to today's advancements in gene programming and stem cell research, each milestone marks a pivotal moment that has reshaped diabetes treatment, improving the quality of life and survival for millions worldwide." (PMID 39734941, 2024). "Meanwhile, insulin resistance associated with diabetes and obesity appears to be due to pathway-selective impairment of PI3K/Akt signaling, whereas SHC/Ras/mitogen activated protein kinase (MAPK) is largely unaffected, thereby tipping the balance of insulin’s actions." (PMID 38952394, 2024). "Thus, it still remains to be solved whether patient socio-economic status may potentially modulate the effect of a diabetes nurse on the chance of timely insulin initiation." (PMID 38116986, 2024). "In addition, the involvement of miR-484 in diabetes is known since it may be a regulator of insulin expression—decreasing it in the pancreatic β cells in response to increased glucose." (PMID 39519313, 2024). "Diabetes Mellitus (DM) is a disorder of multiple etiologies characterized by chronic hyperglycemia resulting from defects in insulin secretion and/or insulin action." (PMID 39712180, 2024). "7S,14R-diHDHA-treated MSCs may not only promote the secretion of insulin, but also have the functions of improving insulin resistance, improving the regulatory functions of the liver and other organs, and reducing the level of blood sugar in diabetes." (PMID 38533089, 2024). "Diabetic foot ulcers (DFUs) are a severe complication of diabetes mellitus (DM), which is characterized by high blood glucose levels due to insufficient insulin." (PMID 39409014, 2024). "Diabetes mellitus is a metabolic condition marked by abnormal glucose homeostasis and is usually characterised by persistent hyperglycaemia, owing to defects in insulin secretion by pancreatic beta cells, lower sensitivity of cell surface receptors to insulin, or both." (PMID 39456664, 2024). "We conclude that weight and IR reduction may be sufficient for diabetes remission after bariatric surgery, but the lack of secretion of insulin and GLP-1, as well as glucagon excess, may cause further glycemic deterioration in T2D patients." (PMID 39598143, 2024). "The interaction between thyroid dysfunction and diabetes is bidirectional, and L-thyroxine treatment may significantly improve insulin sensitivity in patients with hypothyroidism and insulin resistance, suggesting that modulating thyroid status could be a potential strategy for reducing NAFLD risk." (PMID 39744179, 2024). "Diabetes mellitus (DM) is a chronic condition brought on by either insufficient insulin production by the pancreas or inefficient insulin utilization by the body." (PMID 38357091, 2024). "Continuous lactate monitoring (CLM) can be useful to allow persons with diabetes to better judge the impact of their exercise regimen on glycemic control and could be used to adjust insulin administration during exercise and alert people to severe physiological stress." (PMID 38701088, 2024). "To identify potential interorgan signaling factors that mediate the effects of nutrient excess on insulin signaling and sugar tolerance, we performed an in-vivo RNAi-mediated screen of the secretome and receptome in a fly model of diet-induced obesity and diabetes." (PMID 39033139, 2024). "Diabetes mellitus (DM) is a complex metabolic pathology characterized by hyperglycemia fluctuations due to the malfunctioning of insulin production, its activity, or both." (PMID 39796593, 2024). "The PIONEER program was designed to test oral semaglutide in patients at different stages across diabetes natural history (mean diabetes duration, 3.5–15 years) and background treatments (monotherapy, added to 1 or 2 oral glucose-lowering agents, or added to insulin)." (PMID 38892765, 2024).
diabetes (continued). "Our findings show that certain disorders elevate AD and PD risk before AD and PD diagnosis including: insulin and non-insulin dependent diabetes mellitus, noninfective gastro-enteritis and colitis, functional intestinal disorders, and bacterial intestinal infections, among others." (PMID 39371139, 2024). "People may be perceived as having diabetes through factors such as blood glucose monitoring, insulin injections, wearable diabetes technology, dietary choices or restrictions, hypoglycemic episodes, or associated comorbidities, including obesity, acanthosis nigricans, foot ulcers, or dialysis." (PMID 39105174, 2024). "However, they often reported referring patients with uncontrolled HbA1C levels to primary care or endocrinology; those departments were perceived to be more adept at prescribing complex therapies, insulin, and/or additional support services such as diabetes educators and nutritionists." (PMID 38743699, 2024). "Diabetes mellitus (DM) is a chronic metabolic disorder characterized by hyperglycemia resulted from defects in insulin secretion, insulin action, or both." (PMID 39030705, 2024). "This study investigated the associations between non-insulin-based insulin resistance indices (METS-IR, TyG, TG/HDL, and TyG-BMI) and the risk of diabetic nephropathy (DN) in US adults with diabetes mellitus (DM)." (PMID 39720248, 2024). "Similarly, type 1 diabetes and long-lasting type 2 diabetes with prevalent secretory dysfunction are associated with insulin depletion and decreased IGF-1 signaling which could further explain the protective role of diabetes on prostate cancer." (PMID 38935200, 2024). "Diabetes Mellitus (DM) is a metabolic disorder marked by elevated blood sugar levels brought on by perturbations in insulin production, function, or both." (PMID 39518317, 2024). "Diabetes mellitus (DM) is a systemic illness characterized by the body’s incapacity to produce enough insulin or respond to it appropriately." (PMID 39702603, 2024). "Additionally, hypoglycemia induced by insulin in male subjects without diabetes was linked to heightened levels of proinflammatory cytokines, markers of lipid peroxidation, and increased production of ROS." (PMID 38655176, 2024). "In addition, S100B knockout mice, unable to synthesize S100B, are resistant to diabetes induced by streptozotocin, exhibiting enhanced insulin sensitivity, glucose tolerance, prevention of β cell destruction, and lower urine volume, food, and water intake compared to wild-type mice." (PMID 38255850, 2024). "This ability may fail in certain pathological conditions, such as insulin resistance and diabetes, characterized by the absence of response to insulin stimulus and a metabolic rigidity that is often associated with cardiac dysfunction." (PMID 39125765, 2024). "For instance, behaviors such as insulin omission for weight control may be mistakenly interpreted as poor diabetes management rather than indicators of an underlying eating disorder." (PMID 39334618, 2024). "Further, stimulation of skin cultures with TNF and IL-1β, but not with diabetes-associated factors like insulin and glucose, stimulate S100A8 and A9 expression in the skin, supporting the previous notion of an inflammatory-driven pathological overexpression of S100A8 and A9." (PMID 39337466, 2024). "Additionally, patients with diabetes are likely to start taking insulin when their blood sugar level become uncontrolled, which may motivate them to engage in self-care activities to prevent further complications." (PMID 39280819, 2024). "Abnormal FPG concentrations and the risk of insulin resistance related to TNF-α may involve the generation of reactive oxygen species and impairment of insulin signaling through serine phosphorylation, which leads to the development of type 2 diabetes mellitus." (PMID 38542788, 2024). "Diabetes mellitus (DM) is a systemic metabolic disease, where the body becomes incapable of generating an appropriate quantity of insulin." (PMID 38392966, 2024).
diabetes (continued). "Finally, chondroitin sulfate-coated gold nanoparticles might enable oral delivery of insulin, with the potential of revolutionizing diabetes treatment." (PMID 39290144, 2024). "Therefore, individuals with diabetes may initially have poorer dietary habits, which is supported by a subsequent study demonstrating a reverse correlation between insulin resistance and dietary quality." (PMID 38337673, 2024). "Besides, research indicates that Cryptotanshinone may impact insulin signaling and glucose metabolism, generating interest in its potential applications for diabetes and metabolic disease research." (PMID 39421869, 2024). "Diabetes mellitus, a chronic metabolic disorder characterized by persistent hyperglycemia and affecting millions of people worldwide, results either from the body’s inability to produce enough insulin (Type 1 diabetes) or from the body’s cells’ ineffective use of insulin (Type 2 diabetes)." (PMID 39125606, 2024). "Furthermore, CD38 regulates insulin secretion and the progression of diabetes." (PMID 38921477, 2024). "The feature ranking phase indicated age, insulin, and body-mass index as most important predictive factors on both the datasets, suggesting therefore physicians and medical doctors to focus on these elements of clinical records to foresee the duration of diabetes for any possible patient." (PMID 38435625, 2024). "However, even with the maximum non-insulin and insulin therapy, some patients fail to achieve glycemic control, and treatment remains challenging, thus increasing the risk of diabetes-associated diseases." (PMID 39274338, 2024). "Furthermore, carnosine is also involved in regulating glucose and insulin in diabetes." (PMID 38873448, 2024). "However, the impact of high-protein diets or high protein consumption on insulin sensitivity and – risk of – diabetes is not straightforward, as we reviewed 10 years ago." (PMID 39114126, 2024). "Hyperglycemia, insulin resistance, elevated insulin, and insulin-like growth factor-1 (IGF-1) levels, inflammatory cytokines, dyslipidemia, increased leptin, and decreased adiponectin have all been attributed to the increased risk of cancer in patients with diabetes." (PMID 39020360, 2024). "Additionally, the metabolic control of diabetes (e.g., insulin versus non-insulin treatments) may differentially affect bone health, although studies directly comparing these effects are sparse." (PMID 39595124, 2024). "In terms of signaling pathways, and in cases of diabetes, reduced insulin levels and reduced insulin receptor expression are associated with AD and the defective activation of the insulin/IGF-1/PI3K/Akt pathway of intracellular signals, which is a major effector for insulin’s action in the brain." (PMID 39769243, 2024). "The discourse amongst diabetes specialists and academics regarding technology and artificial intelligence (AI) typically centres around the 10% of people with diabetes who have type 1 diabetes, focusing on glucose sensors, insulin pumps and, increasingly, closed-loop systems." (PMID 37979006, 2024). "This hypothesis is supported by observations from other research groups, which have reported an increase in the incidence of diabetes associated with the absence of or significant reduction in insulin secretion in individuals who have recovered from COVID-19." (PMID 39767735, 2024). "In addition to its well-established role in insulin release and diabetes, multiple studies demonstrate a role for this gene in the release of monoamines (dopamine, norepinephrine, and serotonin) in the brain that lead to deficits in learning and memory, and motor behavior." (PMID 39070644, 2024). "Diabetes mellitus (DM) is a group of metabolic disorders characterised by chronic hyperglycaemia resulting from defects in insulin synthesis, insulin action, or both." (PMID 38313813, 2024).